SGMS2 (sphingomyelin synthase 2)
Description:
Sphingomyelin synthase that primarily contributes to sphingomyelin synthesis and homeostasis at the plasma membrane. Catalyzes the reversible transfer of phosphocholine moiety in sphingomyelin biosynthesis: in the forward reaction transfers phosphocholine head group of phosphatidylcholine (PC) on to ceramide (CER) to form ceramide phosphocholine (sphingomyelin, SM) and diacylglycerol (DAG) as by-product, and in the reverse reaction transfers phosphocholine from SM to DAG to form PC and CER. The direction of the reaction appears to depend on the levels of CER and DAG in the plasma membrane. Does not use free phosphorylcholine or CDP-choline as donors. Can also transfer phosphoethanolamine head group of phosphatidylethanolamine (PE) on to ceramide (CER) to form ceramide phosphoethanolamine (CPE). Regulates receptor-mediated signal transduction via mitogenic DAG and proapoptotic CER, as well as via SM, a structural component of membrane rafts that serve as platforms for signal transduction and protein sorting. To a lesser extent, plays a role in secretory transport via regulation of DAG pool at the Golgi apparatus and its downstream effects on PRKD1. Required for normal bone matrix mineralization.
Synonyms: SMS2; MGC26963; CDL
Tractability: Small molecule: a high-quality ligand is known. Antibody: UniProt places it where antibodies can reach, with high confidence; its Gene Ontology location is reachable by antibodies, with high confidence; UniProt predicts a signal peptide or a membrane-spanning region. PROTAC: ubiquitination databases record sites on it; a small molecule that binds it is known.
Target class: Enzyme; Transferase
Gene: Protein-coding gene on chromosome 4 (107,824,563 to 107,915,047, forward strand). Ensembl gene ENSG00000164023.
Subcellular location: Cell membrane; Golgi apparatus membrane
Subcellular location (Human Protein Atlas): Golgi apparatus; Nucleoplasm
Pathways (Reactome):
Metabolism: Sphingolipid de novo biosynthesis
Gene Ontology:
Molecular function: ceramide cholinephosphotransferase activity; protein binding; sphingomyelin synthase activity; ceramide phosphoethanolamine synthase activity; phosphotransferase activity, for other substituted phosphate groups
Biological process: regulation of bone mineralization; sphingomyelin biosynthetic process; ceramide biosynthetic process; sphingolipid biosynthetic process
Cellular component: Golgi apparatus; Golgi membrane; plasma membrane; endoplasmic reticulum membrane
Genetic constraint (gnomAD): Loss-of-function variants: 18 observed, 42.78 expected, observed/expected ratio (o/e) 0.42, 90% interval 0.29 to 0.62. The upper end of that interval is the gene's LOEUF score, 0.62, which puts it in group 2 of 6, group 1 being the genes least tolerant of losing a copy. Missense variants: 378 observed, 458.4 expected, observed/expected ratio (o/e) 0.82, 90% interval 0.76 to 0.9. Synonymous variants: 166 observed, 168.1 expected, observed/expected ratio (o/e) 0.99, 90% interval 0.87 to 1.12.
Homologues: Orthologues: chimpanzee SGMS2 (100% identical), macaque SGMS2 (99% identical), pig SGMS2 (96% identical), dog SGMS2 (96% identical), rabbit SGMS2 (96% identical), mouse Sgms2 (92% identical), rat Sgms2 (91% identical), guinea pig SGMS2 (86% identical), tropical clawed frog sgms2 (78% identical), zebrafish sgms2a (60% identical), zebrafish sgms2b (54% identical), Caenorhabditis elegans sms-1 (34% identical). Paralogues in human: SGMS1 (58% identical), SAMD8 (36% identical).
Diseases named in the same sentence as SGMS2 in open-access papers:
SGMS2 is named in the same sentence as 64 diseases in open-access papers, as found by Europe PMC text mining. Sharing a sentence is not in itself a finding about the gene and the disease. The quoted sentences say what the papers report.
osteoporosis (15 papers, 2019 to 2026). A condition of reduced bone mass, with decreased cortical thickness and a decrease in the number and size of the trabeculae of cancellous bone (but normal chemical composition), resulting in increased fracture incidence. "Recently, rare heterozygous variants in SGMS2, encoding SGMS2, have been identified to cause early-onset osteoporosis or more severe skeletal dysplasia." (PMID 41821748, 2026). "Pathogenic variants in the human SGMS2 gene coding for SMS2 protein result in a rare form of primary osteoporosis, “Calvarial doughnut lesions with bone fragility” (CDL)." (PMID 41143154, 2025). "To date, 3 heterozygous disease-causing SGMS2 variants have been identified: c148C>T (p.Arg50*) leading to early-onset osteoporosis, c.185T>G (p.Ile62Ser) and c.191T>G (p.Met64Arg) leading to a more severe spondylometaphyseal dysplasia." (PMID 40978119, 2025). "Several other novel forms of monogenic osteoporosis have been recently described, for example those caused by variants in SGMS2 and ARHGAP25." (PMID 37668887, 2024). "The molecular and cellular mechanisms behind SGMS2-linked osteoporosis are not fully understood, but it is believed that the onset of the disease is a result of improperly targeted bulk SM production rather than a diminished capacity to synthesize SM." (PMID 37886644, 2023). "Pathogenic heterozygous variants in SGMS2 cause a rare monogenic form of osteoporosis known as calvarial doughnut lesions with bone fragility (CDL)." (PMID 37886644, 2023). "Obviously, the long-term treatment of osteoporosis and the safety of using bisphosphonates in young patients with nucleotide variants in the SGMS2 gene have yet to be evaluated." (PMID 37175737, 2023). "Another recently discovered form relates to disturbed sphingolipid metabolism due to SGMS2 mutations, underscoring the complexity of molecular pathology in monogenic early-onset osteoporosis." (PMID 34236445, 2022). "Here we have expanded the characterization of the tissue‐level bone pathology in patients with primary osteoporosis due to a pathogenic variant in the SGMS2 gene." (PMID 34761145, 2021). "The identification of 6 families with childhood-onset osteoporosis with mutations in SGMS2 suggests a critical role for plasma membrane–bound sphingomyelin metabolism in skeletal homeostasis." (PMID 30779713, 2019). "SGMS2 pathogenic variants underlie a spectrum of skeletal conditions, ranging from isolated osteoporosis to complex skeletal dysplasia, suggesting a critical role for plasma membrane–bound sphingomyelin metabolism in skeletal homeostasis." (PMID 30779713, 2019). "We identified heterozygous pathogenic variants in the SGMS2 gene encoding plasma membrane–resident SMS2 in patients with rare forms of osteoporosis." (PMID 30779713, 2019). "Additionally, germline SGMS2 variants are associated with early-onset osteoporosis and skeletal dysplasia with bone fragility, highlighting the role of plasma-membrane sphingomyelin metabolism in osteoblast/osteocyte biology." (PMID 41463320, 2025). "Heterozygous pathogenic variants in the SGMS2 gene, encoding the sphingomyelin-synthesizing enzyme sphingomyelin synthase 2, cause a rare monogenic form of osteoporosis with low bone density, fractures, bone deformities, sclerotic cranial lesions, and occasionally, neurological symptoms." (PMID 40978119, 2025). "We previously reported that SMS2 is highly expressed in bone and identified heterozygous mutations in the SMS2-encoding gene (SGMS2) as the underlying cause of a clinically described autosomal dominant genetic disorder – osteoporosis with calvarial doughnut lesions (OP-CDL: OMIM #126550)." (PMID 36102623, 2022). "Disruptions in the circadian rhythm can therefore have negative effects on bone turnover and bone matrix mineralization, in line with skeletal features seen in patients with SGMS2-related osteoporosis." (PMID 40978119, 2025).
osteoporosis (continued). "This study examined the cellular mechanisms of SGMS2-related osteoporosis and skeletal dysplasia through transcriptomic and lipidomic profiling of serum and fibroblasts from patients and controls." (PMID 40978119, 2025). "One of the most recently identified genes to cause a rare monogenic form of osteoporosis is SGMS2, which codes for the enzyme sphingomyelin synthase 2 (SMS2)." (PMID 37886644, 2023). "Transiliac and femoral bone biopsy samples from patients with SGMS2-related osteoporosis reveal reduced mineral content and decreased bone volume with unorganized collagenous network." (PMID 37886644, 2023). "Importantly, vertebral compression fractures have been reported as an early and prominent manifestation in several families with SGMS2-related osteoporosis, underscoring its clinical significance in pediatric bone fragility diagnostics." (PMID 41517371, 2025). "A heterozygous SGMS2 pathogenic variant, c.148C>T (p.Arg50*) causes childhood-onset osteoporosis with low BMD and skeletal fragility with or without sclerotic doughnut-shaped lesions." (PMID 40978119, 2025). "Several subjects displayed in addition to osteoporosis, neurological symptoms, e.g. transient facial nerve palsy, suggesting that these extra-skeletal manifestations may be a distinctive feature of SGMS2-related osteoporosis." (PMID 37668887, 2024). "The clinical presentations of SGMS2-related bone pathology range from childhood-onset osteoporosis with low bone mineral density and sclerotic doughnut-shaped lesions in the skull to a severe spondylometaphyseal dysplasia with neonatal fractures, long-bone deformities, and short stature." (PMID 37886644, 2023). "SGMS2-related osteoporosis belongs to this group of monogenic metabolic bone disorders." (PMID 37886644, 2023). "We postulate how disrupted SM gradient can influence bone formation and how animal models may facilitate a better understanding of SGMS2-related osteoporosis." (PMID 37886644, 2023). "Several subjects displayed neurological symptoms, transient facial nerve palsy being particularly common, suggesting that these extra-skeletal disease manifestations may be a distinctive feature of SGMS2-related osteoporosis." (PMID 34236445, 2022). "Collectively, our findings suggest that the underlying cause of osteoporosis and skeletal dysplasia in patients with pathogenic variants in SGMS2 is not a reduced cellular capacity to synthesize sphingomyelin but rather a perturbation in sphingomyelin metabolism at the plasma membrane." (PMID 30779713, 2019). "Patients with skeletal phenotypes and osteoporosis were identified with mutations in the SGMS2 gene encoding for the SMS2, with some sharing the same nonsense variant to yield a catalytically inactive enzyme and presenting with childhood-onset osteoporosis." (PMID 34912800, 2021).
breast carcinoma (14 papers, 2018 to 2025). "To determine the mechanism underlying the role of SGMS2 in promoting EMT in breast cancer cells, we investigated the TGF-β/Smad signalling pathway." (PMID 30770781, 2019). "To further elucidate the exact role of SGMS2 in breast cancer, we carried out gain- and loss-of-function studies in vitro and in vivo." (PMID 30770781, 2019). "A previous study showed that high expression of SGMS2 is associated with breast cancer metastasis." (PMID 36059802, 2022). "have demonstrated that the high expression of SGMS2 was associated with breast cancer metastasis." (PMID 34692520, 2021). "Our primary study indicated that high SGMS2 expression is associated with breast cancer metastasis." (PMID 30770781, 2019). "However, it was intriguing that the expression of SGMS2 was higher in patients with lymph node metastasis than in those without metastasis, which strongly suggests that SGMS2 is associated with tumour metastasis in breast cancer patients." (PMID 30770781, 2019). "Sphingomyelin homeostasis is majorly regulated by the overexpression of sphingomyelin synthase 2 (SMS2) in breast cancer." (PMID 39858015, 2025). "In breast cancer, SGMS2 overexpression increases TGF-β1 level and activates TGF-β/Smad signaling, thereby inhibiting apoptosis and promoting invasiveness." (PMID 41463320, 2025). "SGMS2 enhances the growth and spread of cancer cells in breast cancer by utilizing a mechanism connected with ceramide and activating the TGF-β/Smad signaling pathway." (PMID 38970097, 2024). "In this study, we aimed to investigate the role of sphingomyelin synthase 2 (SMS2) in breast cancer resistance." (PMID 38285090, 2024). "Further studies were applied to determine the effects of SGMS2 on the bioactivities of breast cancer cells." (PMID 30770781, 2019). "A subcutaneous tumour mouse model was used to determine the effect of SGMS2 on the growth of breast cancer cells in vivo." (PMID 30770781, 2019). "We investigated the role of SGMS2 in proliferation and migration of breast cancer cells through both in vitro and in vivo studies and analysed the related signalling pathways that enhance the aggressive of breast cancer cells." (PMID 30770781, 2019). "SGMS2 expression was significantly higher in breast cancer tissues from patients with lymph node or distant metastasis compared with non-metastasis samples (P < 0.001, right)." (PMID 30770781, 2019). "We found that SMPD2, SMPD4, and SMPD5 were significantly higher in breast cancer tissue than that in paired normal breast tissue, while SGMS2 was significantly decreased in breast cancer tissue (TCGA cohort, n=112)." (PMID 29731990, 2018). "In addition, we found that aggressive breast cancer cell phenotypes were recovered when the TGF-β/Smad signalling pathway was specifically arrested in SGMS2 overexpression cells by pirfenidone, and the expression of EMT-related markers was also reversed." (PMID 30770781, 2019). "Thus, we suppose that SGMS2 is quite important in promotion of an aggressive breast cancer cell type by regulating the expression of Cer and SM." (PMID 30770781, 2019). "Additional immunofluorescence assays determined that SGMS2 could facilitate epithelial-to-mesenchymal (EMT) transition in both of the breast cancer cell lines." (PMID 30770781, 2019). "In addition, our studies revealed that SGMS2 significantly promoted in vitro migration, motility and invasiveness of breast cancer cells through EMT." (PMID 30770781, 2019). "However, the mechanism by which SGMS2 promotes breast cancer development and progression remains unknown." (PMID 30770781, 2019). "Thus, our findings indicate that SGMS2-mediated activation of the TGF-β/Smad signalling pathway is important in breast cancer progression, which provides new insight into the mechanisms underlying breast cancer metastasis and suggests a possible anticancer therapy for breast cancer." (PMID 30770781, 2019).
breast carcinoma (continued). "SGMS2 increased the expression of TGF-β1 by upregulating SM, which subsequently activated the TGF-β/Smad signalling pathway and promoted EMT in breast cancer cells, thus increasing the migration and invasiveness of breast cancer cells." (PMID 30770781, 2019). "To determine the role of the TGF-β/Smad signalling pathway in the tumour-promoting effects of SGMS2, we specifically disrupted the TGF-β/Smad signalling pathway using pirfenidone in SGMS2 transient overexpression breast cancer cells." (PMID 30770781, 2019).
atherosclerosis (11 papers, 2011 to 2025). A disease characterized by the build-up of fatty material and calcium deposition in the arterial wall resulting in partial or complete occlusion of the arterial lumen. "Downregulation of SMS2 (SGMS2) activity results in protective effects against obesity, atherosclerosis and diabetes and makes SMS2 inhibitors potential medicines." (PMID 34553271, 2021). "We previously showed that sphingomyelin synthase 2 (SMS 2), an enzyme directly involving in SM de novo biosynthesis, deficiency reduces plasma and cell membrane SM levels, reduces NFκB-, MAP kinase-mediated inflammatory responses, and thus reduces atherosclerosis in mouse models." (PMID 21521522, 2011).
Obesity (11 papers, 2014 to 2024). Accumulation of substantial excess body fat. "SGMS1 is localised in the Golgi apparatus and has previously been related to cell growth, whereas SGMS2 is mainly found at the plasma membrane and has been linked to obesity and insulin resistance." (PMID 33770195, 2021). "Notably, SGMS1-null mice present with insulin secretion deficiencies and mitochondrial dysfunction, whereas SGMS2 knockout mice are protected against high-fat diet-induced obesity and insulin resistance." (PMID 33770195, 2021). "Interestingly, Sgms2 deficiency in mice increases insulin sensitivity and ameliorates high-fat diet-induced obesity and Hadh−/− mice, while having a disrupted β-oxidation pathway, are also protected from diet-induced obesity." (PMID 33143653, 2020). "In female mice, prioritised genes included Sgms2 and Hadh that were found to be involved in various processes, such as increased energy expenditure (MP:0004889), decreased susceptibility to diet-induced obesity (MP:0005659) and increased circulating free fatty acid level (MP:0001554)." (PMID 33143653, 2020). "A puzzling aspect is that removal of Sgms2 in mice ameliorates diet-induced obesity and insulin resistance but is not known to cause any overt bone defect." (PMID 30779713, 2019).
Insulin resistance (7 papers, 2019 to 2025). Increased resistance towards insulin, that is, diminished effectiveness of insulin in reducing blood glucose levels. "Furthermore, GPRC5B facilitates Fyn-dependent phosphorylation of sphingomyelin synthase 2 (SMS2), which activates the diacylglycerol/protein kinase C/c-Jun N-terminal kinase (DAG/PKC/JNK) signaling cascade, a key pathway in the pathogenesis of insulin resistance." (PMID 40864777, 2025).
glioma (3 papers, 2019 to 2022). A benign or malignant brain and spinal cord tumor that arises from glial cells (astrocytes, oligodendrocytes, ependymal cells). "In contrast, SGMS2 tends to be highly expressed in IDHwt gliomas and correlated with deteriorated survival." (PMID 36012521, 2022). "Inhibiting SGMS2 may interfere with the ability of glioma cells to maintain ceramide and SM homeostasis, thus increasing ceramide levels and exceeding the rheostatic threshold necessary for inducing apoptosis." (PMID 36012521, 2022).
ovarian carcinoma (3 papers, 2022 to 2024). A malignant neoplasm originating from the surface ovarian epithelium. "For ovarian cancer, depletion of sphingomyelin synthase 2, which controls SM content, has been shown to suppress survival, growth, and migration of cell lines via disruption of lipid metabolism and mitochondrial function." (PMID 38610937, 2024).
triple-negative breast carcinoma (3 papers, 2022 to 2024). An invasive breast carcinoma which is negative for expression of estrogen receptor (ER), progesterone receptor (PR), and human epidermal growth factor receptor 2 (HER2). "Blocking SGMS2 or genetically eliminating its expression decreases the M2 polarization of tumor-associated macrophages and hinders the advancement of tumors in triple-negative breast cancer (TNBC)." (PMID 38970097, 2024). "In triple negative breast cancer patients, SGMS2 expression was related to immunosuppressive TIME and dissatisfactory survival." (PMID 36056909, 2023).
colitis (2 papers, 2019 to 2024). Inflammation of the colon. "Our finding is consistent with the report that sphingomyelin synthase 2 (SMS2) deficiency inhibited the initiation of DSS-induced colon inflammation by regulating the proinflammatory immune response via inhibition of gene expression." (PMID 30873029, 2019).
fatty liver disease (2 papers, 2016 to 2021). A reversible condition wherein large vacuoles of triglyceride fat accumulate in liver cells via the process of steatosis. "Sphingomyelin synthase 2 (SMS2) is an important enzyme for hepatic sphingolipid homeostasis and its dysfunction is considered to result in fatty liver disease." (PMID 27010944, 2016).